MDM2 (MDM2 proto-oncogene)
Diseases named in the same sentence as MDM2 in open-access papers (continued):
Sharing a sentence is not in itself a finding about the gene and the disease.
cancer (continued). "E3 ligases, or particular components of their complexes (MDM2, IAP, APC/CDC20, and others), are known as oncogenes or tumor suppressors in numerous types of cancer; thus, they may serve as potential cancer targets or are themselves “druggable” enzymes." (PMID 34502538, 2021). "The presented results indicate that, following chemotherapy, MDM2 WT was released from MDM2-NBN complex and efficiently degraded, hence allowing extensive HR DNA repair leading to the acquisition of chemoresistance by cancer cells." (PMID 34572735, 2021). "Cancer cells with MDM2 gene amplification are especially sensitive to Nutlin-induced apoptosis while MDM2 non-amplified cells are resistant to apoptosis but undergo cell cycle arrest." (PMID 34532654, 2021). "We demonstrated that, following treatment with chemotherapeutics, MDM2 is released from the MRN complex in an ATP-dependent reaction, triggering efficient homologous recombination DNA repair, thereby allowing cancer cells to survive the exposure to DNA-damaging drugs." (PMID 34572735, 2021). "Another MDM2 inhibitor, APG-115, can enhance antitumor immunity in the TME by increasing M1 macrophage polarization and T-cell activation and the anti-PD-1-mediated antitumor effect on mouse models of cancer immunotherapy." (PMID 34943817, 2021). "Nutlin treatment blocks autophagy and promotes apoptosis in MDM2-amplified cancer cells but promotes autophagy in MDM2 non-amplified cells that are resistant to apoptosis." (PMID 34532654, 2021). "Previous studies in cancer cells not treated with chemotherapeutics have shown that the interaction between MDM2 and NBN inhibits the repair of DSBs generated during DNA replication in rapidly proliferating cells." (PMID 34572735, 2021). "We identified genes for which ASEs were observed in both the Afro-Caribbean cohort and the Jurkat cells expressing Tax or HBZ, including cancer genes EIF4A2, IKBKB, LZTR1, STAT6 (for Tax); CARS, MDM2, IKZF1 (for HBZ); and EWSR1, MUTYH, and PTPRC (for both Tax and HBZ)." (PMID 34543356, 2021). "Despite progress in MDM2 inhibitor design and ongoing clinical trials, their broad use in cancer treatment is not fulfilling expectations in heterogenous human cancers." (PMID 34911439, 2021). "Again, the simplistic notions of using MDM2 inhibition in cancer therapy are not borne out in the clinic, despite evidence in their favour from in vitro models." (PMID 34911439, 2021). "Based on novel discoveries and recent progress made in cancer biology in the last few years, future work will be required to elucidate the molecular mechanisms of MDM2 and NFAT1 in cancer metabolism and provide molecular insights to guide future single agent or combinatorial treatment options." (PMID 32397368, 2020).
cancer (continued). "Given that the formation of MDM2-MDMX complex stabilizes MDM2 protein, enhances its E3 ubiquitin ligase activity, and promotes the ubiquitination and degradation of MDMX, the MDM2-MDMX binding has been considered as a promising target for cancer therapy." (PMID 32850448, 2020). "The diagnostic accuracy of the six‐member panel of markers (HCCR, C‐myc, MDM2, miR‐21, miR‐223, and miR‐375) for cancer patients with TNM0‐I, Tis‐T1, and negative lymph node metastasis was 87%, 85%, and 84%, respectively." (PMID 31856412, 2020). "We found that PFT-α failed to prevent the effects of Mdm2 inhibitor Nutlin-3 on cell cycle and apoptosis in several cancer cell lines." (PMID 31974452, 2020). "In addition, this review sheds light on the currently available MDM2 and NFAT1 inhibitors and their effects on cancer cells." (PMID 32397368, 2020). "We will also assume that the applied Mdm2 inhibitor has higher uptake by cancer cells, and estimate minimal specificity ratio, cancer-to-normal cells, for the inhibitor to make the combination therapy effective and safe for normal cells." (PMID 32724100, 2020).
cancer (continued). "However, it is unclear if MDM2 also promotes expression of other MYC family members and has similar effects in other cancers." (PMID 33425720, 2020). "As an oncoprotein, MDM2 could contribute DNA damage repair dysfunction and promote cell death by repressing HBP1, which makes it a potential target for cancer therapy." (PMID 30816344, 2019). "Subcellular localization of MDM2 protein in cancer cells was predominantly nuclear with or without cytoplasmic." (PMID 31428819, 2019). "We revealed that there was indeed a significant correlation between FKBP12 and MDM2 expression and that the expression level of FKBP12 in cancer tissue might predict prognosis and response to chemotherapy." (PMID 31428819, 2019). "We further observed a negative correlation between FKBP12 and MDM2 expression, which determined the responsiveness of cancer cells to anticancer treatment." (PMID 31428819, 2019). "Furthermore, our studies have suggested a strong correlation between MDM2 and VEGF in eight different cancer types, implicating a strong role for MDM2 in the regulation of angiogenesis process." (PMID 29748481, 2018). "In agreement with a possible role for these RNA/DNA hybrid-interacting helicases in cancer, analysis of the COSMIC cancer dataset revealed that these DEAD/H helicases are frequently genetically amplified in cancer, similar to known oncogenes SKP2 and MDM2." (PMID 29742442, 2018). "Interestingly, about 85% of MDM2 amplifications co-exist with MDMX amplification, a phenomenon rarely observed in other cancer types." (PMID 29464071, 2018).
cancer (continued). "Both MDM2 and MDMX are frequently found altered in human cancers." (PMID 28673313, 2017). "While upregulation of p14ARF and its binding to Mdm2 in response to oncogenic stresses suggest an important role for p14ARF, anticancer contributions of p14ARF in human cancer are not significant based on current evidence." (PMID 28218667, 2017). "AMPK signaling exerts regulatory effects on cancer cell adhesion, migration and invasion, which is involved in different mechanisms including disruption of the mTOR, TGF-b, Pdlim5, CXCL12, NF-κB and Akt-MDM2-Foxo3a pathways." (PMID 29245964, 2017). "Taken together, our results indicate that dual inhibition of the MDM2–MDMX interaction and the NFAT1–MDM2 interaction might serve as a compelling approach for improving the clinical outcomes of patients with cancer." (PMID 29311926, 2017). "Some cancer patients with MDM2 overexpression have a worse prognosis than patients with cancers that do not have such overexpression." (PMID 28615518, 2017). "Owing to the notion that XIAP and MDM2 typically undergo amplification and/or overexpression in most forms of cancer, these non-transformed, non-tumorigenic cell lines were chosen for their physiological expression of target genes." (PMID 28542129, 2017). "MDM2 and VEGF have been considered as potential cancer targets." (PMID 28274247, 2017).
cancer (continued). "Several studies have suggested that the inhibition of E3 ligases may cause growth suppression or cell death, as evidenced by the over-expression of Mdm2/Hdm2, IAPs, and SCF in various human cancers." (PMID 26818115, 2016). "In addition, when compared with other MDM2 antagonists RG7388 and Nutlin-3, which have demonstrated significant efficacy in a variety of cancer types in vitro, SAR405838 had shown a similar inhibitory effect on NB cells." (PMID 27764791, 2016).